ING5 (inhibitor of growth family member 5)
Diseases named in the same sentence as ING5 in open-access papers (continued):
Sharing a sentence is not in itself a finding about the gene and the disease.
gastric cancer (13 papers, 2015 to 2022). A primary or metastatic malignant neoplasm involving the stomach. "We also constructed ING5 variants according to the protein domains and clarified the effects of these domains on the phenotypes of gastric cancer cells." (PMID 35747809, 2022). "Disruption of ING5 function has also been linked to several types of cancers, particularly gastric cancers." (PMID 27310475, 2016). "The low nuclear expression of ING5 and its nucleocytoplasmic translocation were observed in the tumorigenesis of breast cancer, head and neck squamous cell carcinoma, colorectal cancer, and gastric cancer, and closely linked to invasion and metastasis." (PMID 35747809, 2022). "ING5 deletion in parietal, stem-like, and Pdx1-positive cells of gastric epithelium might contribute to the histogenesis of gastric cancer, and increase the susceptibility to chemically induced gastric carcinogenesis." (PMID 35747809, 2022). "ING5 overexpression has been reported to inhibit aggressive phenotypes of gastric cancer cells by β-catenin, NF-κB, and Akt pathways." (PMID 35747809, 2022). "ING5, SRF, and YY1 were overexpressed in gastric cancer, (P<0.05), and associated with worse prognosis of gastric cancer patients (P<0.05)." (PMID 35747809, 2022). "Although the nucleocytoplasmic translocation of ING5 protein appeared from gastric mucosa, dysplasia to cancer, ING5 was observed to be upregulated in gastric cancer in comparison with the level in paired mucosa at both mRNA and protein levels." (PMID 35747809, 2022). "Taking these findings together, we concluded that ING5 functions as a tumor suppressor in gastric cancer." (PMID 35747809, 2022). "Next, we found that ING5 mRNA expression was higher in gastric cancer than in normal tissues, even when stratified into intestinal-, diffuse-, and mixed-type carcinoma using Cho’s datasets (P<0.05)." (PMID 35747809, 2022). "To clarify why ING5 is up-regulated in gastric cancer, we predicted the promoter sequence and screened its activity." (PMID 35747809, 2022). "Reportedly, ING5 was found to repress proliferation, and elevate autophagy and apoptosis in gastric cancer cells." (PMID 32308564, 2020). "The hypoexpression of nuclear ING5 protein and its nucleocytoplasmic translocation were observed in colorectal and gastric cancers, and closely correlated with their aggressive behaviors or adverse prognosis." (PMID 28915612, 2017). "The resulted chemoresistance in gastric cancer was also evidenced in the suppression of ING5, which stimulated tumor cell migration and invasion in concurrence with the inhibition of autophagy." (PMID 28076332, 2017). "The nuclear to cytoplasmic shift of ING5 protein occurred during colorectal, gastric and HNSCC carcinogenesis and was positively linked to the aggressive behaviors of colorectal and gastric cancers." (PMID 27409347, 2016). "ING5 overexpression reverses the aggressive phenotypes of gastric cancer cells such as autophagy and proliferation, dedifferentiation, migration, invasion and lamellipodia formation." (PMID 27409347, 2016). "Here, we found that ING5 overexpression increased autophagy, differentiation, and decreased proliferation, apoptosis, migration, invasion and lamellipodia formation in gastric cancer cells, while ING5 knockdown had the opposite effects." (PMID 25980581, 2015). "The pEGFP-N1-ING5 transfection and nucleocytoplasmic fraction demonstrated that ING5 protein was localized in the nuclei of gastric cancer or epithelial cells, indicating that the translocating system of ING5 protein works well in the cells." (PMID 25980581, 2015).
gastric cancer (continued). "ING5 might be used as a target for the anti-tumor effect of SAHA in gastric cancer cells if its promoting effects on migration and invasion are avoided or ameliorated." (PMID 35747809, 2022). "The low expression of CDC2, VEGF, and MMP-9 might account for the inhibitory effects of WT and mutant ING5 on the proliferation and invasion of gastric cancer." (PMID 35747809, 2022). "Therefore, we can confidently employed ING5 as a biomarker for aggressiveness and prognosis of gastric cancer and a target of gene therapy for gastric cancer patients." (PMID 35747809, 2022). "Finally, we clarified the effects of ING5’s domains on the phenotypes of gastric cancer cells and ING5 knockout on gastric carcinogenesis using conditional knockout (KO) mice." (PMID 35747809, 2022). "In combination with the findings in gastric cancer cells, it should be possible and practicable to employ ING5 as a potential target for gene therapy of malignancies if its chemoresistance could be dislodged." (PMID 27409347, 2016). "ING5 expression was higher in gastric cancer than matched mucosa." (PMID 25980581, 2015). "Statistically, ING5 expression was higher in gastric cancer than the matched mucosa (p < 0.05)." (PMID 25980581, 2015). "ING5 expression was also compared with carcinogenesis and aggressive behaviors of gastric cancer." (PMID 25980581, 2015). "ING5 might induce apoptotic and chemotherapeutic resistances of gastric cancer cells by activating β-catenin, NF-κB and Akt pathways." (PMID 25980581, 2015). "In the present study, we observed the in vivo and vitro effects of altered ING5 expression on proliferation, apoptosis, autophagy, differentiation, invasion, migration, metastasis and chemoresistance of gastric cancer cells, and analyzed the relevant molecular mechanisms." (PMID 25980581, 2015). "The reduction in nuclear ING5 expression and its cytoplasmic translocation were observed in head and neck squamous cell cancer (HNSCC), and positively linked to tumorigenesis and aggressive behaviors of colorectal or gastric cancers." (PMID 25980581, 2015). "ING5 deletion might contribute to the tumorigenesis and histogenesis of gastric cancer." (PMID 35747809, 2022). "ING5 overexpression might activate β-catenin, NF-κB and Akt pathways in gastric cancer." (PMID 25980581, 2015). "In conclusion, ING5 overexpression might suppress the proliferation, migration and invasion, induce autophagy and differentiation, and mediate apoptotic and chemotherapeutic resistance of gastric cancer cells." (PMID 25980581, 2015). "Therefore, it has to be careful to employ ING5 as a target of gene therapy for gastric cancer." (PMID 25980581, 2015). "In TCGA data, there was a positive correlation between ING5 and YY1 mRNA expression in gastric cancer (P<0.05)." (PMID 35747809, 2022). "There was also a positive correlation between ING5 and SRF mRNA expression in gastric cancer (P<0.05)." (PMID 35747809, 2022). "Cytoplasmic translocation of ING5 had impact on the carcinogenesis of HNSCC and CRCs and cytoplasmic ING5 was positively correlated with the aggressive behaviors of CRC and gastric cancers." (PMID 27409347, 2016).
gastric cancer (continued). "However, ING5 overexpression was found in gastric cancer in comparison to matched mucosa by Western blot, which might be attributable to its nucleocytoplasmic translocation from NLS mutation, ING5 expression in stromal cells and a high karyoplasmic ratio of cancer cells." (PMID 25980581, 2015). "The synergistic effects of ING5 and SAHA were also determined in gastric cancer cells." (PMID 35747809, 2022). "In gastric cancer cells, either SRF or YY1 silencing decreased ING5 mRNA and protein expression." (PMID 36425530, 2022). "According to the bioinformatics findings, the expression of ING5, SRF, and YY1 mRNA was higher in gastric cancer than in normal mucosa, and negatively associated with favorable prognosis of gastric cancer patients." (PMID 35747809, 2022). "ING5 had positive relationships with SRF and YY1 expression in gastric cancer (P<0.05)." (PMID 35747809, 2022). "The overexpression of PI3K, p-Akt, p70S6K and nPKC in ING-5-overexpressing SGC-7901 demonstrated that Akt/PI3K/p70S6K activation and nPKC overexpression might enhance the apoptotic and chemotherapeutic resistance of gastric cancer cells." (PMID 25980581, 2015). "ING5 overexpression was in vitro found to decrease migration, invasion and lamellipodia formation with MMP-9 hypoexpression, and in vivo suppressed lung metastasis of gastric cancer cells, suggesting that ING5 might inhibit invasion and metastasis of gastric cancer by reducing MMP-9 expression." (PMID 25980581, 2015).
colorectal cancer (12 papers, 2011 to 2026). A primary or metastatic malignant neoplasm that affects the colon or rectum. "Based on existing studies, NOB1 was found to be associated with the 26S proteasome to inhibit apoptosis and ING5 may related to EGFR/PI3K/Akt pathway in colorectal cancer to induce apoptosis." (PMID 33996574, 2021). "Further studies have demonstrated that ING5 exhibits nuclear-cytoplasmic dual expression in colorectal cancer, with a positive rate significantly higher than that in hepatocellular carcinoma and other cancers." (PMID 41614944, 2026). "In contrast, ING5 also enhanced the self-renewal of glioblastoma stem cells 16 and induced the chemoresistance of colorectal cancer cells according to our unpublished data." (PMID 39247819, 2024). "In conclusion, miR-196b-5p promotes cell proliferation, migration, invasion, and inhibits apoptosis in colorectal cancer by targeting ING5." (PMID 32308564, 2020). "MiR-196b-5p was abundantly expressed in colorectal cancer tissues and cell lines, whereas ING5 was expressed at low levels." (PMID 32308564, 2020). "Although the anti-apoptosis protein Bcl-2, which was a direct target of miR-1307, had been reported to be over-expressed in colorectal cancer, we found that ING5 was a target gene of miR-1307 by means of chip analysis and Target Scan software." (PMID 28086946, 2017). "We further confirmed the changes of these EMT markers at protein level by western blot in ING5-overexpressing and -knockdown A549 cells, ING5-overexpressing colorectal cancer HCT116 cells, and their corresponding control cells." (PMID 25938545, 2015). "Aberrant ING5 expression was also thought to contribute to pathogenesis, growth, and invasion of gastric carcinomas and colorectal cancer." (PMID 25938545, 2015). "Moreover, ING5 overexpression inhibited colorectal cancer progression via inactivation of PI3K/Akt pathway." (PMID 39247819, 2024). "At the translational level, both miR-196 and miR-196b-5p target ING5 in colorectal cancer cells." (PMID 36425530, 2022). "In addition, aberrant ING5 expression was thought to contribute to pathogenesis, growth, and invasion of gastric carcinomas and colorectal cancer." (PMID 21750715, 2011). "Moreover, ING5 overexpression or knockdown was successfully performed in colorectal cancer cells." (PMID 32308564, 2020). "Down-regulated expression of nuclear ING5 protein was observed in oral Sq, HNSCC and colorectal cancer (CRC) respectively." (PMID 27409347, 2016).
ovarian carcinoma (12 papers, 2017 to 2024). A malignant neoplasm originating from the surface ovarian epithelium. "As a whole, the results indicated that loss of ING5 expression promoted cell proliferation, inhibited cell apoptosis, and promoted chemoresistance in ovarian cancer cells." (PMID 28086946, 2017). "miR-429 targets the 3’-UTR of ING5 directly and inhibits ING5 expression in ovarian cancer epithelial cells, thereby mediating tumorigenesis and cell proliferation." (PMID 37737712, 2023). "As for the clinicopathological and prognostic significances, ING5 mRNA expression was negatively correlated with vascular and lymphatic invasion, and clinicopathological staging of ovarian cancers." (PMID 36425530, 2022). "Another study in ovarian cancer cells has shown that the up-regulation of ING5 suppresses the viability of malignant cells and reduces their glucose metabolism, migratory potential, invasiveness, and EMT." (PMID 35804879, 2022). "ING5 is the target gene of miR1307, and miR1307 can inhibit apoptosis in ovarian cancer cells by down-regulating the expression of ING5." (PMID 34576121, 2021). "Previous studies have revealed that miR-1307 participates in ovarian cancer cell proliferation and apoptosis through targeting ING5." (PMID 32308564, 2020). "In summary, our findings suggest that miR-200b/200a/429 is an oncogenic miRNA that significantly contributes to ovarian cancer development by targeting ING5." (PMID 32377191, 2020). "To further explore the mechanism, we analyzed the protein expressions following different miR-1307 treatment in various kinds of ovarian cancer cells, and the results indicated the downstream gene ING5 of miR-1307 in vitro." (PMID 28086946, 2017). "Our findings demonstrated that ING5 up-regulated LC-3B, Beclin 1 and ATG13 expression with autophagy strengthened in ovarian cancer cells, indicating that ING5 induced autophagy in Beclin 1-dependent manner." (PMID 29262575, 2017). "ING5 mRNA level was lower in ovarian cancer than normal ovary, and borderline than benign tumors (p < 0.05), and inversely linked to the differentiation of ovarian cancer (p < 0.05)." (PMID 29262575, 2017). "We subcutaneously transplanted ovarian cancer cells and their ING5 transfectants into nude mice, and found that the tumor volume and weight of ING5 transfectants were larger than the control by rule measurement, calculation and weighting (p < 0.05)." (PMID 29262575, 2017). "ING5 overexpression reduced cell viability and induced apoptosis of ovarian cancer cells than the control and mock (p < 0.05)." (PMID 29262575, 2017). "Our results showed that ING5 level was lower in ovarian cancer than normal ovary at both mRNA and protein, while cytoplasmic and nuclear ING5 expression was immunohistochemically increased from normal ovary, ovarian benign and borderline tumors to cancer." (PMID 29262575, 2017). "ING5 overexpression induced autophagy according to the morphological appearance of ovarian cancer cells after the transient transfection of GFP-tagged LC-3B plasmid." (PMID 29262575, 2017). "ING5 overexpression suppressed tumor growth of ovarian cancer by decreasing proliferation, and inducing apoptosis and autophagy." (PMID 29262575, 2017). "To identify novel biomarkers for cancer diagnosis and novel targets for treatment, we observed the effects of ectopic ING5 overexpression on the aggressive phenotypes of ovarian cancer cells, and analyzed the relevant mechanisms." (PMID 29262575, 2017). "We found that PI3K, Akt, and β-catenin were decreased in ING5 transfectants of ovarian cancer cells." (PMID 29262575, 2017). "ING5 mRNA level was lower in ovarian cancer than normal ovary, and borderline than benign tumors (p < 0.05), and negatively correlated with vascular invasion, lymphatic invasion and FIGO staging of ovarian cancer (p < 0.05)." (PMID 29262575, 2017).